SNORD67 (small nucleolar RNA, C/D box 67)
Synonyms: HBII-166
Gene: Small nucleolar RNA gene on chromosome 11 (46,762,389 to 46,762,499, reverse strand). Ensembl gene ENSG00000212135.
Gene Ontology:
Biological process: RNA processing
Cellular component: nucleolus
Homologues: Orthologues: chimpanzee SNORD67 (100% identical), macaque SNORD67 (99% identical), rabbit SNORD67 (98% identical), dog SNORD67 (97% identical), mouse Snord67 (97% identical), pig SNORD67 (96% identical), rat Snord67 (96% identical), guinea pig SNORD67 (95% identical).
Diseases named in the same sentence as SNORD67 in open-access papers:
SNORD67 is named in the same sentence as 6 diseases in open-access papers, as found by Europe PMC text mining. Sharing a sentence is not in itself a finding about the gene and the disease. The quoted sentences say what the papers report.
breast carcinoma (1 paper, 2025). "In breast cancer cell lines, Snord67 knockout results in loss of targeted 2′-O-methylation on U6 small nuclear RNA, as well as widespread changes in splicing." (PMID 40316533, 2025). "Further studies will be needed to elucidate the contribution of specific Snord67-associated splice variants to the Snord67-dependent promotion of breast cancer lymphatic metastasis." (PMID 40316533, 2025). "We then evaluated the functional significance of loss of Snord67 or Snord111 in breast cancer cells." (PMID 40316533, 2025). "Together, these results suggest that high Snord67 expression is associated with decreased survival in subsets of patients with aggressive breast cancer subtypes, notably HER2-enriched and Luminal B." (PMID 40316533, 2025). "We further demonstrate that loss of Snord67 in breast cancer cell lines leads to decreased colony formation and spheroid area in vitro, as well as decreased lymph node tumor growth and distant metastases in murine models." (PMID 40316533, 2025). "We found that loss of Snord67 leads to changes in the splicing landscape of both murine and human breast cancer cells, resulting in differential alternative splicing of cassette exons as well as decreased overall intron retention." (PMID 40316533, 2025). "In an orthotopic breast cancer model, loss of Snord67 decreases LN metastasis." (PMID 40316533, 2025). "Interestingly, high expression of the Snord67 host gene CKAP5 was associated with significantly worse overall survival in HER2-enriched breast cancer, consistent with previous results showing that CKAP5 expression is associated with poor prognosis in non-small cell lung cancer." (PMID 40316533, 2025). "To evaluate the function of these snoRNAs in 4T1 breast cancer cells, we generated Snord67 and Snord111 knockout clones using the CRISPR/Cas9 system." (PMID 40316533, 2025). "To examine the impact of Snord67 knockout on gene expression and splicing patterns in a human breast cancer cell line, we performed RNA-seq in D3H2 WT cells and Snord67 knockout cells." (PMID 40316533, 2025). "Together, our results reveal that Snord67 promotes the lymphatic dissemination of breast cancer and suggest the Snord67-mediated regulation of splicing as a potential mechanism." (PMID 40316533, 2025). "We found that exon 40 in the MYO18A gene and exon 3 in the NFYA gene were not only downregulated in Snord67 knockout cells, but also positively correlated with Snord67 expression levels in breast cancer patients." (PMID 40316533, 2025). "Here the authors show that the snoRNA Snord67 promotes lymph node metastasis of breast cancer cells through guiding modifications of the spliceosome and regulating the splicing landscape." (PMID 40316533, 2025). "To more directly evaluate the relevance of Snord67 expression to patients with breast cancer, we examined data from breast cancer patients in The Cancer Genome Atlas (TCGA)." (PMID 40316533, 2025). "Snord67 expression is enriched in LN metastases in an immune-competent mouse model of female breast cancer." (PMID 40316533, 2025). "In the HER2-enriched subtype of breast cancer, tumors with high Snord67 expression trended toward decreased overall survival, but this difference was not statistically significant." (PMID 40316533, 2025). "Taken together, these results support a model in which differential expression of Snord67 leads to differential alternative splicing not only in murine and human breast cancer cell lines, but also in patients with breast cancer." (PMID 40316533, 2025). "In patients with breast cancer, increased Snord67 expression may similarly lead to decreased splicing efficiency and alternative splicing, resulting in more aggressive tumor phenotypes." (PMID 40316533, 2025).
breast carcinoma (continued). "Since Snord67 knockout was associated with differential alternative splicing in both murine and human breast cancer cell lines, we considered whether these same alternative splicing events correlated with Snord67 expression in humans with breast cancer." (PMID 40316533, 2025). "To replicate these findings in a human breast cancer model, we generated a Snord67 knockout clone in MDA-MB-231-D3H2LN-luc (D3H2), a cell line that spontaneously metastasizes to loco-regional lymph nodes and was derived from the human triple-negative breast adenocarcinoma model MDA-MB-23133." (PMID 40316533, 2025). "Thus, the EO771.LMB murine breast cancer cell line exhibits in vitro phenotypes similar to the 4T1 cell line upon Snord67 knockout and rescue." (PMID 40316533, 2025). "We further validate two Snord67-dependent differential alternative splicing events that also correlate with Snord67 expression in paired primary breast and lymph node tumors from patients with breast cancer." (PMID 40316533, 2025). "Here, we identify the snoRNA Snord67 as a regulator of lymph node (LN) metastasis in breast cancer." (PMID 40316533, 2025). "Notably, Snord67 and CKAP5 expression were highly correlated in breast cancer patients." (PMID 40316533, 2025). "Although we have shown in several models that loss of Snord67 impacted phenotypes independent of CKAP5 host gene expression, the correlation of Snord67 and CKAP5 expression in breast cancer patients raises the possibility that Snord67 expression may be co-regulated with expression of its host gene." (PMID 40316533, 2025).
breast tumors (1 paper, 2025). "Moreover, the change in PSI for these two alternative exons significantly correlated with the change in Snord67 expression in matched pairs of primary breast tumors and LN metastases (MYO18A exon 40: Pearson r = 0.54, p = 0.0066; NFYA exon 3: Pearson r = 0.51, p = 0.011)." (PMID 40316533, 2025). "That is, in patients whose LN metastasis displayed increased Snord67 expression relative to the primary breast tumor, the inclusion of MYO18A exon 40 and NFYA exon 3 was also increased in the LN tumor relative to the primary breast tumor." (PMID 40316533, 2025). "Although Snord67 expression was not increased in the LN relative to the primary breast tumor for all patients, the upregulation of Snord67 may be one of several possible mechanisms that promote lymphatic metastasis." (PMID 40316533, 2025).
triple-negative breast carcinoma (1 paper, 2025). An invasive breast carcinoma which is negative for expression of estrogen receptor (ER), progesterone receptor (PR), and human epidermal growth factor receptor 2 (HER2). "Taken together, our findings demonstrate that Snord67 is required for 2′-O-methylation at C60 in U6 snRNA and that Snord67 promotes colony and spheroid formation in murine and human triple-negative breast cancer cell lines." (PMID 40316533, 2025).
cancer (1 paper, 2025). A tumor composed of atypical neoplastic, often pleomorphic cells that invade other tissues. "To evaluate whether Snord67 may play a role in distant metastasis colonization after the cancer cells leave the LN and enter the circulation, we tested the effect of Snord67 loss on the establishment of metastases after tail vein injection." (PMID 40316533, 2025). "Using an assay to detect luciferase activity in cancer cells that had metastasized to the lungs, we found that mice injected with Snord67 knockout cells also developed significantly fewer distant lung metastases four weeks after AxLN injection." (PMID 40316533, 2025). "Furthermore, the observation that the mutant Snord67 construct can still partly rescue in vitro phenotypes raises the possibility that other, non-canonical mechanisms may contribute to the role of Snord67 in cancer cells." (PMID 40316533, 2025).
tumor (1 paper, 2025). "Since both remodeling of the extracellular matrix and dysregulation of cytokine signaling have been implicated in tumor progression and metastasis, Snord67 may promote metastasis in part by regulating the expression of genes involved in these pathways." (PMID 40316533, 2025). "In a model of lymphatic metastasis, Snord67 loss decreases LN tumor growth and distant metastases." (PMID 40316533, 2025). "Mice treated with 24 and 48 mpk of Snord67 ASO demonstrated significantly reduced tumor growth at 20 days post-LN injection, compared to vehicle-treated mice." (PMID 40316533, 2025). "In particular, we propose that the loss of Snord67-guided 2′-O-methylation of U6 C60 and the resulting changes in splicing are responsible for the decrease in LN tumor growth and LN-derived distant metastases observed upon Snord67 knockout." (PMID 40316533, 2025). "To evaluate the effect of Snord67 on LN tumor growth and distant metastasis in vivo, we micro-injected 4T1 WT or Snord67 knockout cells expressing mCherry and Renilla luciferase into the AxLN of immune-competent mice." (PMID 40316533, 2025). "Together, these results demonstrate that loss of Snord67 expression, whether by CRISPR knockout or by ASO treatment, leads to decreased AxLN tumor growth in a microsurgical, immune-competent murine model of LN metastasis." (PMID 40316533, 2025). "We then evaluated the effect of Snord67 expression on growth and metastasis from the primary tumor." (PMID 40316533, 2025). "In a subset of patients, the upregulation of Snord67 in LN metastases may lead to changes in the splicing landscape, which in turn promote LN tumor growth and distant metastasis." (PMID 40316533, 2025). "From our initial screen for ncRNAs that are differentially regulated in LN tumors, we identified the box C/D snoRNA Snord67 as having essential roles for tumor growth and survival in LNs, and perhaps even more importantly, for subsequent metastasis to distant sites." (PMID 40316533, 2025). "Since the observed tumor growth phenotypes could be due to the isolation of clonal populations of Snord67 knockout cells, we also used an alternative approach by abruptly inhibiting Snord67 expression with an ASO." (PMID 40316533, 2025). "Notably, we found that the snoRNAs Snord67 and Snord111 were upregulated both in micro-injected LNs and in de novo LN metastases, raising the possibility that the LN microenvironment induces the upregulation of these snoRNAs, perhaps as an adaptive mechanism in tumor cells." (PMID 40316533, 2025). "Although the EO771.LMB Snord67 knockout clone and one 4T1 Snord67 knockout clone demonstrated significantly decreased MFP tumor growth after mammary fat pad injection, MFP tumor growth was unaffected in the second 4T1 Snord67 knockout clone." (PMID 40316533, 2025). "To determine whether Snord67 and Snord111 expression also increased in de novo LN metastases, we measured expression of these snoRNAs by RT–qPCR in matched pairs of MFP tumor subclones and de novo LN metastasis subclones." (PMID 40316533, 2025). "However, in contrast to LN tumor growth after AxLN micro-injection, MFP tumor growth was not clearly affected by loss of Snord67." (PMID 40316533, 2025). "Together, these results demonstrate that Snord67 decreases de novo LN metastases but does not clearly affect MFP tumor growth or distant metastases arising from the MFP, suggesting that the role of Snord67 on tumor growth and metastasis may be specific to the LN environment." (PMID 40316533, 2025).
SNORD67 also shares sentences with these, for which no sentence is quoted: lymph node tumor (1 paper).